SIRT1 (sirtuin 1)
Diseases named in the same sentence as SIRT1 in open-access papers (continued):
Sharing a sentence is not in itself a finding about the gene and the disease.
hepatocellular carcinoma (continued). "Studies have shown that the expression of Sirt1 has a beneficial effect in terms of weakening osteoporosis in rats, the formation of fear memory in mice, and delaying the senescence of hepatocellular carcinoma (HCC) cells." (PMID 33562281, 2021). "More importantly, miR-124 overexpression suppressed the expression of SIRT1 and thus promoted the phosphorylation of JNK and finally sensitized cisplatin-induced cytotoxicity against CD133+ hepatocellular carcinoma cells." (PMID 33345272, 2021). "In our study, we assessed 6 biomarkers (LAPTM4B, RANKL, OPG, YKL-40, VIT D, and SIRT1), LAPTM4B was first identified as a hepatocellular carcinoma-related gene in mammals." (PMID 32102511, 2020). "In contrast, another recent data showed that Sirt1 interacts with HIF‐1α and the deacetylation of HIF‐1α stabilizes HIF‐1α protein expression and promotes its activity using human hepatoma cell lines such as Hep3B, HepG2, and Huh7 cells." (PMID 30614190, 2019). "In hepatocellular cancer cell lines (HepG2, Bel-7402, SMMC-7721), RES activated SIRT1 protein and inhibited SIRT1-mediated post-translational modification of PI3K/AKT signaling." (PMID 31159437, 2019). "HBV-associated chromatin modifying enzymes of PCAF, p300/CBP, HDAC1, SIRT1, and EZH2 have been shown to bind to the cccDNA in human hepatoma cells containing replicating HBV49." (PMID 30115977, 2018). "The clinical value of SIRT1 in hepatocellular carcinoma (HCC) remains controversial." (PMID 28881735, 2017). "In hepatocellular carcinoma (HCC), SIRT1 is overexpressed in malignant tissue as compared with normal liver, and its expression is significantly correlated with tumor size, tumor number, stage, and poor prognosis." (PMID 27379175, 2016). "A PLA assay performed on the human hepatocellular carcinoma cell line HepG2, which endogenously expresses FOXA2 and SIRT1, showed interaction of these proteins." (PMID 24875183, 2014). "Moreover, the expression of lncRNA HULC, regulated by miR-6825-5p, miR-6845-5p, and miR-6886-3p, elevates the deubiquitination effect of USP22 on SIRT1, making hepatocellular carcinoma (HCC) cells resistant to oxaliplatin and inducing protective autophagy in HCC cells." (PMID 38702734, 2024). "Rats fed with fructose in drinking water, Sirt1−/− mice, mice treated with the ER stressor tunicamycin with or without a SIRT1 activator, and human Huh-7 hepatoma cells transfected with siRNA or exposed to tunicamycin or different inhibitors were used." (PMID 38807218, 2024). "Additionally, studies have demonstrated that CPEB1 can directly target SIRT1, suppressing its translation and mediating cancer stemness in vitro and in vivo, suggesting its potential as a therapeutic target in hepatocellular carcinoma (HCC)." (PMID 38994352, 2024). "Moreover, USP22 directly interacts with sirtuin 1 (SIRT1) and positively regulates SIRT1 protein expression, leading to activation of the SIRT1/AKT/ABCC1 pathway and MDR of hepatocellular carcinoma." (PMID 36694209, 2023). "Besides, SIRT1 activated RANBP2, indispensable for FTO SUMOylation at Lysine (K)−216 site, to enhance FTO degradation, leading to progression of hepatocellular carcinoma." (PMID 35945194, 2022). "With the accumulated evidence about SIRT1's function in cancer, EX-527 and other SIRT inhibitors have been studied as potential therapies in multiple cancer cells, including melanoma 35, hepatocellular carcinoma 36, chronic lymphocytic leukemia 37, and lung cancer." (PMID 32863939, 2020). "In an orthotopic xenograft model of hepatocellular carcinoma (HCC), SIRT1 knockdown resulted in 50% fewer animals developing tumours, and small molecule inhibitor cambinol treatment resulted in an overall lower tumour burden, suggesting that SIRT1 expression positively affects the growth of HCC." (PMID 27793039, 2016).
hepatocellular carcinoma (continued). "Indeed, exposure to high glucose (35mM) led to a decrease in SIRT1 expression while simultaneously stimulating PIAS4 expression in both primary mouse hepatocytes and immortalized hepatocellular carcinoma cells (HepG2)." (PMID 27285989, 2016). "Using the same approach, several cellular transcription factors (CREB, ATF, YY1, STAT1, and STAT2) and chromatin modifying enzymes (PCAF, p300/CBP, HDAC1, SIRT1, and EZH2) have been shown to bind to the cccDNA in human hepatoma cells containing replicating HBV." (PMID 24133502, 2013). "The regulatory effects of adiponectin, Sirt1, and AMPK found in rat hepatoma cells are intriguing, but, future studies are needed to investigate whether this regulation is RGZ-dependent." (PMID 21373642, 2011). "Current strategies for modulating sirtuin activity in the treatment of hepatocellular carcinoma (HCC) and non-alcoholic fatty liver disease (NAFLD) focus on the activation and inhibition of specific sirtuins, particularly SIRT1 and SIRT2, respectively." (PMID 40136715, 2025). "Here, we report that in hepatocellular carcinoma (HCC) cells under glucose-deprived conditions, SCIC2.1 treatment induced overexpression of SIRT1, SIRT3, and SIRT6, modulating metabolic response." (PMID 37715252, 2023). "Also, SIRT1 negatively regulates GH-induced IGF-1 mRNA production, which was confirmed in a human hepatocellular carcinoma cell line (HepG2) and rat primary hepatocytes, with the use of SIRT1 inhibitors (sirtinol and nicotinamide) and stimulators (resveratrol and NAD)." (PMID 37895086, 2023). "The negative impact of SIRT1 on GH-induced IGF-1 mRNA expression was also confirmed by the same team in HepG2 (human hepatocellular carcinoma cell line) and rat primary hepatocytes with use of SIRT1 inhibitors (sirtinol, nicotinamide) and stimulators (resveratrol, NAD)." (PMID 29932147, 2018). "Moreover, in rat hepatoma cells, adiponectin activated AMPK signaling by up-regulating Sirt1." (PMID 21373642, 2011). "Other groups found SIRT1 expression to be significantly elevated in hepatocellular carcinoma (HCC) compared to non-cancerous tissues, the expression levels correlated with tumor grades and predicted poor prognosis." (PMID 24603648, 2014). "Our results show that in hepatocellular carcinoma (HCC) cell lines, hypoxia did not alter SIRT1 mRNA or protein expression, whereas it predictably led to the accumulation of HIF-1α and the up-regulation of its target genes." (PMID 22479397, 2012). "Recently, interactions between SIRT1 and PGC-1α have attracted much attention in the study of tumorigenesis, as an SIRT1/PGC-1α-dependent increase in mitochondrial biogenesis and OXPHOS enhanced the chemoresistance of colon cancer and metastasis of hepatocellular carcinoma (HCC)." (PMID 35681729, 2022).
endothelial dysfunction (146 papers, 2010 to 2026). In vascular diseases, endothelial dysfunction is a systemic pathological state of the endothelium (the inner lining of blood vessels) and can be broadly defined as an imbalance between vasodilating and vasoconstricting substances produced by (or acting on) the endothelium. "Intriguingly, the overexpression of nicotinamide phosphoribosyltransferase (Nampt) and activation of SIRT1 rescues polyploidy-associated endothelial dysfunction, which is reminiscent of the anti-senescent role of this cascade." (PMID 37894840, 2023). "Age-associated endothelial dysfunction in mice has been linked to lower SIRT1 expression and eNOS activity." (PMID 38304233, 2023). "Such age-related SIRT1 repression is associated with human endothelial dysfunction, as determined by impaired flow-mediated vasodilation in the forearms." (PMID 37894840, 2023). "Nevertheless, evidence points to associations of serum sirtuin-1 levels with protection against chronic diseases and markers of aging and endothelial dysfunction." (PMID 35683374, 2022). "MTHFR C677T carriers with normal Hcy levels revealed endothelial dysfunction and enhanced platelet aggregation associated with SIRT1 downregulation." (PMID 35821533, 2022). "Further evidence showed that loss of function of SIRT1 is implicated in several pathological processes, such as endothelial dysfunction, atherosclerosis, cardiovascular diseases, hypercholesterolemia, hypertension, diabetes mellitus, obesity, among others." (PMID 35683374, 2022). "By targeting SIRT1, miR-200 decreases NO and increases the acetylation of SIRT1 targets, thus causing ROS generation and endothelial dysfunction." (PMID 34069422, 2021). "Sirt1-mediated p66Shc reduction is associated with the prevention of OS-mediated endothelial dysfunction and senescence, as well as the pathophysiological process of PCOS." (PMID 32066482, 2020). "In summary, endothelial SIRT1-deficiency, a model of global endothelial dysfunction, leads to upregulation of syndecan-4 and release of its ectodomain, the loss of the EG through increased superoxide generation and induced NF-κB signaling." (PMID 32494847, 2020). "TMAO also increases the oxidative stress of endothelial cells through a down-regulation of SIRT-1 and impairs NO production that causes endothelial dysfunction." (PMID 31234461, 2019). "All endothelial functions (deterrent of leukocytes, regulation of permeability and vasomotion, angiogenesis, platelet adhesion and coagulation) become perturbed in SIRT1 deficiency, thus being responsible for global endothelial dysfunction." (PMID 30298020, 2018). "This spectrum of abnormalities associated with SIRT1 deficiency in endothelial cells is essential for understanding the origins and features of endothelial dysfunction in a host of cardiovascular and renal diseases." (PMID 30298020, 2018). "Previous documents proven that Sirt1-dependent mechanism was wide agreement in DM-associated endothelial dysfunction, therefore we added Sirt6 mRNA- containing EMPs into Sirt1 deficient HUVECs." (PMID 29371988, 2017). "In the present study, 8 weeks of NMN supplementation restored a marker of arterial SIRT1 activity and ameliorated age‐associated endothelial dysfunction and large elastic artery stiffening in male C57Bl/6 mice." (PMID 26970090, 2016). "Decreased expression of SIRT1 is associated with endothelial dysfunction in arteries from aged mice and humans." (PMID 25926556, 2015). "A SIRT1 upregulation and/or activation is associated with EC functional preservation; whereas excessive ROS or aging decrease SIRT1 expression, leading to endothelial dysfunction." (PMID 24734227, 2014). "It has been described that oxidative stress is one of the causes that induces a downregulation of SIRT1 expression in endothelium and a main source of endothelial dysfunction, while defects in endothelial SIRT1 activity can trigger an increase in ROS production and vascular inflammation." (PMID 36829935, 2023).
endothelial dysfunction (continued). "Metformin recovered those detrimental changes, protected against endothelial dysfunction, and ultimately repaired the impaired lung functions, and the underlying mechanisms may be related to the activation of SIRT1." (PMID 35910360, 2022). "SIRT1 is implicated in the regulation of endothelial dysfunction and cardiovascular diseases." (PMID 36359987, 2022). "MiR-34 downregulates SIRT1, causing hyperglycemia-induced vascular cell senescence; miR-204 promotes endothelial dysfunction and vascular ER stress; and miR-106b overexpression increases the oxidative stress induced by high glucose levels in NIT-1 cells, a mouse pancreatic β-cell line." (PMID 34069422, 2021). "However, SIRT1 overexpression led to recovery of impaired vascular dysfunction by reducing eNOS acetylation and elevating its bioavailability, which suggests that SIRT1 is a key modulator of CRIF1 deficiency-induced endothelial dysfunction." (PMID 29474366, 2018). "We hypothesized that SIRT1 activation could improve the cardiovascular risk profile and reverse or improve the vascular and endothelial dysfunction associated with cigarette smoking." (PMID 23770971, 2013). "Moreover, sirtuin 1 (SIRT1), a nicotinamide adenosine dinucleotide (NAD)-dependent deacetylase, may cause synergetic effects of aging on endothelial dysfunction in hypertension since the age-related loss in SIRT1 is associated with increased senescence." (PMID 34203897, 2021). "Thus, repression of secretory profiles (consisting of soluble factors and MP) may contribute to the anti-aging effect of SIRT1, leading to protection against the endothelial dysfunction of age-associated vascular diseases." (PMID 28811647, 2017). "In conclusion, inhibition of VEGFR signalling induces oxidative stress and PARP activation, leading to SIRT1 downregulation, endothelial dysfunction and vascular inflammation." (PMID 42307134, 2026). "SIRT1, through its deacetylase activity, regulates eNOS, which increases nitric oxide production, promoting vasodilation and protecting against endothelial dysfunction." (PMID 40076724, 2025). "Elevated miR-92a levels can cause endothelial dysfunction by targeting genes such as Krüppel-like factor 2 (KLF2), KLF4, and sirtuin 1 (SIRT1)." (PMID 41425580, 2025). "This study uncovers CHKA as a pivotal driver of vascular dysfunction in diabetic retinopathy and highlights its role in endothelial dysfunction through NAD+‐SIRT1‐Notch signaling." (PMID 40548950, 2025). "Growing evidence links them to molecular and vascular ageing, including oxidative stress, endothelial dysfunction, and reduced expression of longevity-related proteins like Klotho and SIRT1." (PMID 41002407, 2025). "Acetylation, particularly at lysine 81, is counterbalanced by the NAD+‐dependent deacetylase SIRT1 and mainly influences p66Shc function in regulating oxidative stress and endothelial dysfunction, especially in diabetic disease." (PMID 40690563, 2025). "Endothelial dysfunction is prevented by dapagliflozin A (SGLT2) inhibitors via SIRT1 activation, and it is ameliorated by restoring eNOS activity, NO bioavailability, and decreased ROS production." (PMID 41567643, 2025). "MiR-92a inhibits Sirt1 and endothelial nitric oxide synthase and also activates inflammasomes, which exacerbates endothelial dysfunction under oxidative stress." (PMID 40217882, 2025).
endothelial dysfunction (continued). "Recent studies indicate a link between these conditions and endothelial dysfunction, oxidative stress, mitochondrial dysregulation, and altered expression of key longevity regulators such as Klotho and SIRT1." (PMID 41002407, 2025). "The functional study showed that Tempol (100 μM), Resveratrol (20 μM), and SIRT1 OE adenovirus (MOI 100) significantly reversed K.pn EV-induced endothelial dysfunction." (PMID 39800699, 2025). "To further confirm the involvement of SIRT1 in K.pn EV-induced endothelial dysfunction, we determined the protein levels both in the presence and absence of SIRT1 overexpression." (PMID 39800699, 2025). "Taken together, these results suggest that SIRT1 mediates K.pn EV-induced endothelial cell senescence and endothelial dysfunction." (PMID 39800699, 2025). "In this review we focus on the biological functions of Sirt1 and we also provide an insight into its role in preventing endothelial dysfunction, as well as the therapeutic strategies of targeting Sirt1 to counteract vascular aging." (PMID 39273039, 2024). "By aging, the expression levels of Sirt1 decline with a severe impact on vascular function, such as the rise of endothelial dysfunction, which in turn promotes the development of cardiovascular diseases." (PMID 39273039, 2024). "In fact, several risk factors for developing a CVD are linked to the rise of oxidative stress, due to an increase in ROS, which promotes vascular aging and endothelial dysfunction and suppresses Sirt1 expression." (PMID 39273039, 2024). "The activation of Sirt1 was able to revert the endothelial dysfunction by diminishing oxidative stress and inflammation, potentiating also eNOS expression." (PMID 39273039, 2024). "Consistently, it has been reported that, in animal models, calorie restriction inhibits the decline of Sirt1 levels in arteries and consequent endothelial dysfunction by counteracting oxidative stress." (PMID 39273039, 2024). "More recently, the transgenic mouse model was used to investigate the impact of SIRT1 overexpression in endothelial dysfunction-induced cardiac dysfunction." (PMID 38304233, 2023). "Overexpression of miR-34a and miR-217 contributes to the progression of endothelial dysfunction by suppressing SIRT1." (PMID 38139440, 2023). "Through a complex epigenetic control mainly involving p66Shc and Arginase II, SIRT1 regulates the levels of mitochondrial ROS and NO, and the expression of key proteins from the mitochondria respiratory chain, subsequently restoring endothelial dysfunction." (PMID 38304233, 2023). "Over-expression of SIRT1 can reduce angiotensin II-mediated inflammation and endothelial dysfunction." (PMID 36580159, 2023). "Upregulation of SIRT1 expression or increase in the activity inhibited endothelial dysfunction stimulated by oxidative stress." (PMID 38095615, 2023). "High glucose exposure induces endothelial dysfunction and decreases vascular SIRT1 expression, which in turn accelerates functional abnormalities." (PMID 37401647, 2023). "An upregulation of SIRT1 in endothelium has been demonstrated to prevent the endothelial dysfunction in vivo and to counteract the increase in stiffness of the large arteries, thus preventing two key age-related changes in the vasculature." (PMID 36829935, 2023). "Caloric restriction effectively counteracts SIRT1 arterial decline and endothelial dysfunction by decreasing the oxidative stress in in vivo animal models." (PMID 36829935, 2023). "According to the conducted studies, SIRT1 increases nitric oxide (NO) production by activating endothelial nitric oxide synthase (eNOS), which leads to vasodilation and a decrease in endothelial dysfunction degree." (PMID 38139440, 2023). "SIRT1 has been involved in protection against myocardial infarction and reperfusion injury, endothelial dysfunction and thrombosis." (PMID 37193033, 2023). "According to previous research, a deficiency in SIRT1 and p-AMPK has been linked to endothelial dysfunction." (PMID 37106756, 2023).